OR2AJ1 (olfactory receptor family 2 subfamily AJ member 1)
Description:
Odorant receptor.
Synonyms: OR2AJ1P; OR2AJ1Q
Tractability: Antibody: UniProt places it where antibodies can reach, with medium confidence; UniProt predicts a signal peptide or a membrane-spanning region; its Gene Ontology location is reachable by antibodies, with medium confidence.
Gene: Protein-coding gene on chromosome 1 (247,924,889 to 247,935,339, forward strand). Ensembl gene ENSG00000177275.
Subcellular location: Cell membrane
Pathways (Reactome):
Sensory Perception: Expression and translocation of olfactory receptors
Gene Ontology:
Molecular function: olfactory receptor activity; G protein-coupled receptor activity
Biological process: detection of chemical stimulus involved in sensory perception of smell; G protein-coupled receptor signaling pathway
Cellular component: plasma membrane; membrane
Homologues: Orthologues: chimpanzee OR2AJ1 (94% identical), rat Or2aj4 (77% identical), mouse Or2aj4 (76% identical), rat Or2aj4b (75% identical), mouse Or2aj6 (74% identical), mouse Or2aj5 (73% identical), dog OR2AJ7 (69% identical). Paralogues in human: OR2L8 (52% identical), OR2L2 (51% identical), OR2L13 (51% identical), OR2L3 (51% identical), OR2L5 (51% identical), OR2T1 (50% identical), OR2T27 (50% identical), OR2T10 (48% identical), OR2T12 (48% identical), OR2T33 (48% identical), OR2T4 (48% identical), OR2AE1 (48% identical), and 80 more.